CDC42EP3 (CDC42 effector protein 3)
Description:
Probably involved in the organization of the actin cytoskeleton. May act downstream of CDC42 to induce actin filament assembly leading to cell shape changes. Induces pseudopodia formation in fibroblasts.
Synonyms: BORG2; CEP3; UB1
Tractability: Antibody: UniProt places it where antibodies can reach, with high confidence; its Gene Ontology location is reachable by antibodies, with high confidence; the Human Protein Atlas places it where antibodies can reach. PROTAC: ubiquitination databases record sites on it.
Gene: Protein-coding gene on chromosome 2 (37,641,882 to 37,738,468, reverse strand). Ensembl gene ENSG00000163171.
Subcellular location: Endomembrane system; Cytoplasm, cytoskeleton
Subcellular location (Human Protein Atlas): Actin filaments; Plasma membrane
Pathways (Reactome):
Signal Transduction: CDC42 GTPase cycle; MAPK6/MAPK4 signaling; RHOQ GTPase cycle
Gene Ontology:
Molecular function: protein binding; cytoskeletal regulatory protein binding; small GTPase binding
Biological process: positive regulation of actin filament polymerization; positive regulation of pseudopodium assembly; regulation of cell shape; Rho protein signal transduction; signal transduction
Cellular component: actin cytoskeleton; plasma membrane; cytoplasm; cytoskeleton; cytosol; endomembrane system
Genetic constraint (gnomAD): Loss-of-function variants: 4 observed, 16.44 expected, observed/expected ratio (o/e) 0.24, 90% interval 0.12 to 0.56. The upper end of that interval is the gene's LOEUF score, 0.56, which puts it in group 2 of 6, group 1 being the genes least tolerant of losing a copy. Missense variants: 309 observed, 323.05 expected, observed/expected ratio (o/e) 0.96, 90% interval 0.87 to 1.05. Synonymous variants: 145 observed, 136 expected, observed/expected ratio (o/e) 1.07, 90% interval 0.93 to 1.22.
Homologues: Orthologues: chimpanzee CDC42EP3 (100% identical), macaque CDC42EP3 (99% identical), guinea pig CDC42EP3 (96% identical), pig CDC42EP3 (95% identical), rat Cdc42ep3 (94% identical), dog CDC42EP3 (94% identical), mouse Cdc42ep3 (93% identical), rabbit CDC42EP3 (89% identical), tropical clawed frog cdc42ep3 (74% identical), zebrafish cdc42ep3 (50% identical). Paralogues in human: CDC42EP2 (38% identical), CDC42EP1 (25% identical), CDC42EP4 (22% identical), CDC42EP5 (18% identical), C15orf62 (13% identical).
Diseases named in the same sentence as CDC42EP3 in open-access papers:
CDC42EP3 is named in the same sentence as 21 diseases in open-access papers, as found by Europe PMC text mining. Sharing a sentence is not in itself a finding about the gene and the disease. The quoted sentences say what the papers report.
colorectal cancer (5 papers, 2021 to 2023). A primary or metastatic malignant neoplasm that affects the colon or rectum. "Further analysis revealed that high CDC42EP3 expression was positively linked to advanced tumor grade, indicating CDC42EP3 as a tumor promotor in colorectal cancer." (PMID 33726765, 2021). "Additionally, CDC42EP3 is also associated with the occurrence and progression of human cancers, such as colorectal cancer, ovarian cancer, and glioma." (PMID 36062142, 2022). "However, except for this, the association between CDC42EP3 and human cancer, including colorectal cancer is still largely unknown, the exploration of which could extend the understanding of CDC42EP3 in cells." (PMID 33726765, 2021). "The silencing of CDC42EP3 in colorectal cancer cell lines further clarified its effects on the phenotype of colorectal cancer cells such as cell proliferation, apoptosis, cell cycle and cell migration." (PMID 33726765, 2021). "First, we detected CDC42EP3 expression in colorectal cancer tissues relative to normal tissues and found significantly upregulated CDC42EP3 in former by IHC analysis." (PMID 33726765, 2021). "CDC42EP3 expression and the connection to tumor characteristics of colorectal cancer patients displayed a correspondence between the appearance of CDC42EP3 and tumor grade in addition to more mesenteric lymph nodes." (PMID 33726765, 2021). "In conclusion, our study revealed that CDC42EP3 played a critical role in the development and progression of colorectal cancer." (PMID 33726765, 2021). "It has also been shown that the up-regulated CDC42EP3 in colorectal cancer tissues can promote tumor growth by regulating cell proliferation, apoptosis, and migration." (PMID 34616622, 2021). "As far as we know, this study is the first one to comprehensively investigate the role of CDC42EP3 in colorectal cancer." (PMID 33726765, 2021). "At the same time, the data from in vivo experiments based on mice xenograft model were in line with those from in vitro experiments, consistently reflecting the suppression effects of CDC42EP3 knockdown on the development and progression of colorectal cancer." (PMID 33726765, 2021). "The expression of CDC42EP3 was distinctly higher in colorectal cancer cell lines than normal cell line." (PMID 33726765, 2021). "In order to better understand the relationship of CDC42EP3 in the development of colorectal cancer, IHC analysis was undertaken on 97 colorectal cancer tissues and 75 normal tissues as a means to identify observable CDC42EP3 expressions." (PMID 33726765, 2021). "CDC42EP3 was identified in both normal tissues and colorectal cancer tissues, showing obviously higher expression in colorectal cancer tissues." (PMID 33726765, 2021). "The subsequent in vitro experiments indicated that CDC42EP3 knockdown in colorectal cancer cells significantly slowed down the growth rate, increased the percentage of apoptotic cells via the activation of apoptosis-related proteins, and hindered cell migration." (PMID 33726765, 2021). "Herein, this study demonstrated that CDC42EP3 may play a role as a tumor promotor in the development and progression of colorectal cancer, which provided a reference for CDC42EP3 as a novel therapeutic target in the treatment of colorectal cancer." (PMID 33726765, 2021). "Feng’s group revealed that CDC42EP3 was significantly up-regulated in colorectal cancer, and its high expression could accelerate cancer progression through regulating cell proliferation, apoptosis, and migration." (PMID 34616622, 2021). "CDC42EP3′s upregulation emphasizes its possible role in the growth of colorectal cancer." (PMID 33726765, 2021). "In all, these conclusions indicate that the lentivirus expressing shCDC42EP3 could significantly downregulate the expression of CDC42EP3 in colorectal cancer cells." (PMID 33726765, 2021).
colorectal cancer (continued). "Similarly, upregulated CDC42EP3 was identified in colorectal cancer cell lines (i.e., HCT116 and RKO) and inhibition in tumor cell growth and migration in vitro could be attributed to CDC42EP3 knockdown." (PMID 35365622, 2022). "In recent years, limited reports have shown that CDC42EP3, a member of the same family as CDC42EP4, is highly expressed in gastric cancer, gliomas, and colorectal cancer." (PMID 38153517, 2023). "Therefore, CDC42EP3 may be used as novel therapeutic target in the treatment of colorectal cancer." (PMID 33726765, 2021). "Noteworthy, although the overexpression of Cdc42 in colorectal cancer and its clinical relevance have been studied to some extent, the role of CDC42EP3 in colorectal cancer has not been reported, which attracted our attention." (PMID 33726765, 2021).
glioma (4 papers, 2008 to 2023). A benign or malignant brain and spinal cord tumor that arises from glial cells (astrocytes, oligodendrocytes, ependymal cells). "Besides, our findings also uncovered that regulation of CDC42EP3 may be associated with stemness of human glioma cells." (PMID 35365622, 2022). "Our findings provided preliminary insights into regulation of CDC42EP3 in human glioma and available references for the development of targeted therapy in glioma." (PMID 35365622, 2022). "The results of statistical analysis also indicated that the expression pattern of CDC42EP3 was more likely to be high in glioma tissues than that in normal brain tissues." (PMID 35365622, 2022). "In this study, we found a much higher possibility of CDC42EP3 upregulation in glioma tissues than that in normal brain tissues." (PMID 35365622, 2022). "In summary, we demonstrated that CDC42EP3 downregulation inhibited the malignant behaviors of glioma cells through regulating c-Myc-mediated transcription of CCND1." (PMID 35365622, 2022). "Further studies on detailed underlying regulatory pathways are required for potentially identifying CDC42EP3 as a therapeutic target in glioma treatment." (PMID 35365622, 2022). "It was suggested that regulation of CDC42EP3 in human glioma cells had something to do with the canonical NF-κB inflammatory pathway." (PMID 35365622, 2022). "Glioma patients with high expression of CDC42EP3 underwent much shorter overall survival and more likely to suffer from tumor recurrence (p < 0.001) than those with low level of CDC42EP3." (PMID 35365622, 2022). "Rescue experiments were finally executed to verify the role played by CDC42EP3/CCND1 axis in human glioma U251 cells." (PMID 35365622, 2022). "Herein, we examined the expression of CDC42EP3 in human glioma clinical samples and in vitro alterations in cell proliferation, cell cycle, cell migration and apoptosis after building CDC42EP3-knockdown cell models via lentiviral transfection." (PMID 35365622, 2022). "Here, we probed the role of CDC42EP3 (CDC42 effector protein 3) played in glioma development and its potential downstream mechanism." (PMID 35365622, 2022). "All of the results above indicated that knocking down CCND1 retarded pro-tumor effects mediated by upregulated CDC42EP3 in glioma." (PMID 35365622, 2022). "Peptide masses of calcium binding protein p22, Cdc42 effector protein 3, fibronectin precursor, and myosin-9 are exclusively present in glioma vessels." (PMID 18312684, 2008). "To examine the role of CDC42EP3 played in glioma cells, we firstly identified the expression level of CDC42EP3 through immunohistochemical staining on clinical samples and found that CDC42EP3 was lower expressed in normal brain tissues than that in glioma tissues." (PMID 35365622, 2022). "In addition, the higher pathological grade of glioma was, the more likely CDC42EP3 was upregulated in patients (p < 0.001)." (PMID 35365622, 2022). "In addition, the higher grade of glioma was, the more likely CDC42EP3 was overexpressed in the clinical samples." (PMID 35365622, 2022). "As a result, our findings indicated that CDC42EP3 may be a tumor-promoting factor in glioma progression via mediating CCND1." (PMID 35365622, 2022). "Specifically speaking, the stemness-related regulators, CD133, MELK and SOX2 were substantially downregulated following transfection of shCDC42EP3-harboring lentivirus into SHG-44 cells, indicating concurrent reduction in expression of CDC42EP3 and stemness of glioma stem cells." (PMID 35365622, 2022). "Moreover, the analysis using RNA-seq data of TCGA also indicated the upregulation of CDC42EP3 in glioma and its correlation with poor prognosis, with an AUC (area under the ROC curves) of 0.735." (PMID 35365622, 2022).
glioma (continued). "After infecting CDC42EP3-targeting lentivirus into human glioma SHG-44 and U251 cells, we established CDC42EP3-depleting cell models and found that lowered CDC42EP3 confined cell proliferation and migration while amplified cell apoptosis via trapping cell cycle in G2 stage." (PMID 35365622, 2022). "On the other hand, considering the significant regulation of cell phenotypes by CDC42EP3 knockdown, it was demonstrated that the regulatory effects of CDC42EP3 knockdown on glioma failed on condition of CCND1 overexpression, indicative of the key role played by CCND1 in downstream of CDC42EP3." (PMID 35365622, 2022). "However, the role played by CDC42EP3 in human glioma development is not yet clear." (PMID 35365622, 2022).
breast carcinoma (3 papers, 2021 to 2023). "In breast cancer cells, Cdc42ep3 or Cdc42ep5 have also been implicated in promoting the septin-actin association." (PMID 36923257, 2023). "In vivo “admix” experiments with breast cancer cells demonstrated that Cdc42EP3 is required for efficient tumor growth." (PMID 34566889, 2021).
gastric cancer (3 papers, 2021 to 2023). A primary or metastatic malignant neoplasm involving the stomach. "A recent study on gastric cancer reported that CDC42EP3 was upregulated in tumor tissues and high level of CDC42EP3 was also connected with the tumor pathological grade." (PMID 35365622, 2022).
ovarian carcinoma (3 papers, 2021 to 2025). A malignant neoplasm originating from the surface ovarian epithelium. "Together, these findings suggest that CDC42EP3, which is correlated with immune-associated molecules, can serve as a potential immunotherapeutic target for treatment of ovarian cancer." (PMID 34616622, 2021). "The expression of CDC42EP3 was found to be down-regulated in ovarian cancer tissues and cells, and its low level was associated with poor prognosis." (PMID 34616622, 2021). "Intriguingly, through the integrative bioinformatics and experimental analysis, the expression of CDC42EP3 was found to be down-regulated in ovarian cancer tissues and cells, and its low level was associated with poor prognosis." (PMID 34616622, 2021). "Furthermore, the expression of CDC42EP3 is obviously associated with TILs, which profoundly affect the prognosis of ovarian cancer." (PMID 34616622, 2021). "Furthermore, a study conducted a bioinformatics analysis of the m6A target gene cell division cycle 42 effector protein (CDC42EP3) in ovarian cancer and discovered that its down-regulation was associated with NK cell infiltration and the promotion of ovarian cancer progression." (PMID 39904996, 2025). "According to UCLCAN database, we discovered that the higher tumor grade, the lower expression levels of CDC42EP3 in ovarian cancer." (PMID 34616622, 2021). "Cell division cycle 42 effector protein 3 (CDC42EP3), one probable m6A target gene, was identified to be down-regulated in ovarian cancer tissues and cells." (PMID 34616622, 2021). "Next, TNM plot revealed that CDC42EP3 mRNA expression levels were significantly down-regulated in ovarian cancer samples." (PMID 34616622, 2021). "In this research, we firstly indicated the clinical prognostic value and potentially functional roles of CDC42EP3 in ovarian cancer through a comprehensive bioinformatics analysis." (PMID 34616622, 2021). "In conclusion, this is the first study to investigate the clinical prognostic roles of CDC42EP3 in ovarian cancer." (PMID 34616622, 2021). "Meanwhile, quantitative PCR (qPCR) and western blot were used to confirm the down-regulated CDC42EP3 in ovarian cancer cells A2780 and TOV112D." (PMID 34616622, 2021). "In order to explore the biological functions of CDC42EP3 in ovarian cancer, we performed the co-expression pattern of CDC42EP3 screened from the TCGA-OV cohort by the LinkFinder module of LinkedOmics." (PMID 34616622, 2021). "The biological function of CDC42EP3 in ovarian cancer was further validated with several algorithms, such as PrognoScan, K-M plotter, LinkedOmics and TISIDB." (PMID 34616622, 2021). "To further elaborate the potential biological roles of CDC42EP3 in ovarian cancer development, we performed GO and KEGG functional enrichment analysis." (PMID 34616622, 2021). "All these data revealed that the expression of CDC42EP3 was significantly downregulated in ovarian cancer tissues and cell lines." (PMID 34616622, 2021). "We explored whether CDC42EP3 expression can affect the abundance of tumor-infiltrating lymphocytes (TILs) in ovarian cancer using Xiantao Tool." (PMID 34616622, 2021). "Generally, we concluded that CDC42EP3 might participated in modulating diverse of immunoregulatory molecules in ovarian cancer, which could affect the infiltration and functions of immune cells in TME." (PMID 34616622, 2021). "Demographic characteristics of CDC42EP3 expression in ovarian cancer." (PMID 34616622, 2021). "Collectively, these results indicate that CDC42EP3 could be a potential prognostic biomarker for ovarian cancer, especially like the high-grade patients." (PMID 34616622, 2021). "However, the detailed roles of CDC42EP3 in human gynecological tumors, especially ovarian cancer, have been rarely studied." (PMID 34616622, 2021). "Furthermore, we analyzed the correlation between CDC42EP3 expression levels and clinicopathological features of ovarian cancer patients." (PMID 34616622, 2021).
ovarian carcinoma (continued). "CDC42EP3 is down-regulated in ovarian cancer tissues and cells, and may serve as a promising prognostic biomarker for ovarian cancer patients." (PMID 34616622, 2021). "The purpose of this study was to investigate the potential roles of CDC42EP3 in ovarian cancer." (PMID 34616622, 2021). "In addition, qPCR and western blot were used to confirm the down-regulation of CDC42EP3 expression in ovarian cancer cells A2780 and TOV112D compared with the normal ovarian epithelial cell IOSE80." (PMID 34616622, 2021). "The results revealed that CDC42EP3 expression had significant prognostic value and could be a promising target for immune regulation in ovarian cancer." (PMID 34616622, 2021). "The correlations between the expression levels of RFXANK, CDC42EP3 and BAMBI and prognosis in ovarian cancer patients were analyzed by the PrognoScan database." (PMID 34616622, 2021). "Given the up-regulated RFXANK and down-regulated CDC42EP3 and BAMBI in two independent ovarian cancer datasets from Oncomine, we expected CDC42EP3 as a potential prognostic target that needs further investigation." (PMID 34616622, 2021). "However, the detailed function and mechanism of CDC42EP3 in the tumorigenesis and immune infiltration of ovarian cancer have not yet been investigated." (PMID 34616622, 2021).
hepatocellular carcinoma (2 papers, 2020 to 2021). A malignant tumor that arises from hepatocytes. "The expression level of CDC42EP3 was up-regulated in primary cultured hepatocellular carcinoma cells and can enhance the cellular migratory ability in vitro." (PMID 34616622, 2021).
chronic lymphocytic leukemia (1 paper, 2021). "In contrast, the expression of CDC42EP3 was down-regulated in peripheral blood monocyte from patients with chronic lymphocytic leukemia, which may be associated with impairment of phagocytosis." (PMID 34616622, 2021). "Conversely, down-regulated CDC42EP3 was found in patients with chronic lymphocytic leukemia." (PMID 34616622, 2021).
leukemia (1 paper, 2013). A malignant (clonal) hematologic disorder, involving hematopoietic stem cells and characterized by the presence of primitive or atypical myeloid or lymphoid cells in the bone marrow and the blood. "Some were already associated with T-CD8+ leukemias (Il2ra; and Pdgfrb) and others were associated with other types of T-leukemias or cancer (Irf4, Hrb, Depdc6, Als2cl, Tle4 and Cdc42ep3), thus validating our approach." (PMID 23902727, 2013).
melanoma (1 paper, 2025). A malignant, usually aggressive tumor composed of atypical, neoplastic melanocytes. "Notably, Cdc42EP5 (also known as BORG3) has a similar role in melanoma metastasis as does Cdc42EP3 in promoting cancer-associated fibroblast activation." (PMID 39971161, 2025). "While the synergy or redundancy of Cdc42EP3 and SEPT9 remains to be determined, Cdc42EP5 has similar roles as SEPT9 in melanoma cells, where both Cdc42EP5 and SEPT9 are required for actomyosin-driven cell migration." (PMID 39971161, 2025).